LPL (lipoprotein lipase)
Diseases named in the same sentence as LPL in open-access papers (continued):
Sharing a sentence is not in itself a finding about the gene and the disease.
diabetes (continued). "The drawback with this approach is that it measures LPL released from all tissues (skeletal muscle, adipose tissue, heart), and hence is incapable of establishing if diabetes specifically influences cardiac LPL." (PMID 34356640, 2021). "Three proteins, lipoprotein lipase, IGF-binding protein 2 and paraoxonase 3 (PON-3), were inversely associated with diabetes." (PMID 31446444, 2019). "LPL-mediated lipolysis and LDL-C–lowering mechanisms independently contribute to the risk of coronary disease and diabetes, which supports the development of LPL-enhancing agents for use in the context of LDL-C–lowering therapy." (PMID 30326043, 2018). "We found that levels of most DAG, TAG, and LPL species in skeletal muscle are increased in the presence of diabetes." (PMID 27388225, 2016). "The results of one study that investigated the effect of statins on changes in LPL mass concentration in patients with diabetes showed results that were contrary to ours." (PMID 27039080, 2016). "In obese subjects with type 2 diabetes mellitus, circulating AngII levels correlate with changes in body weight and tend to correlate negatively with change in LPL." (PMID 26447765, 2015). "Increased lipasin in diabetes inhibits LPL in cardiac and skeletal muscles, hydrolyzing less circulating TAG in TAG-rich lipoproteins, resulting in higher plasma TAG levels." (PMID 26687026, 2015). "The mechanisms of fasting and postprandial increases of TG and intestine-derived lipoproteins in diabetes are supposed to be slower clearance of these particles and/or a reduced activity of lipoprotein lipase (LPL) specifically related to type 2 diabetes." (PMID 23734746, 2013). "Furthermore, diabetes renders lipoprotein lipase inactive, an enzyme crucial for triglyceride breakdown." (PMID 39822379, 2024). "Preventive approaches targeting activation of LPL might be appropriate for these patients before the onset of diabetes." (PMID 39557295, 2024). "This review will cover the participation of LPL in FA delivery to the heart (for generation of energy) and adipose tissue (for storage as TG), and the consequences of its tissue mismanagement following diabetes." (PMID 39081272, 2024). "Thus, approaches that maintain cardiac LPL would be a useful therapeutic approach to preventing cardiac pathology seen following diabetes that is poorly controlled." (PMID 39081272, 2024). "Thus, following severe diabetes, when cardiac LPL action is reduced, NEFA uptake and oxidation takes precedence over provision of FAs to the heart from circulating lipoproteins." (PMID 39081272, 2024). "The prevalence of diabetes, more specifically uncontrolled or poorly controlled T2DM, has been reported in up to 76% of patients with severe HTG and is thought to be exacerbated by the combination of LPL deficiency and continued increased dietary fat intake." (PMID 38911361, 2024). "Similarly, LPL expression in the heart of the rats with streptozotocin-induced diabetes was significantly increased." (PMID 37686357, 2023). "Additionally, the diabetes condition makes the triglyceride-hydrolyzing enzyme lipoprotein lipase ineffective." (PMID 36983154, 2023). "In addition, plasma EL and LPL concentrations, as well as apolipoproteins levels, were measured and the association between these markers and CAD or diabetes was also established." (PMID 37686357, 2023). "LPL may represent a new therapeutic target for treating glucose metabolism disorders, including type 2 diabetes mellitus and hepatic steatosis, such as non-alcoholic fatty liver disease." (PMID 36099304, 2022). "In our study, women with diabetes had higher NEFA at baseline than men, and differences in regional and plasma LPL activity may underlie more rapid catabolism of plasma VLDL1-TG in women." (PMID 34657182, 2022). "Besides severe diabetes, a decline in LPL has also been observed in animals infused with Intralipid." (PMID 34356640, 2021).
diabetes (continued). "As the chronic management of glycemia fluctuates over the duration of diabetes, with frequent episodes of insufficient or poor control, pathological oscillations in coronary LPL arise during this disease to disturb cardiac metabolism and initiate heart failure." (PMID 34356640, 2021). "Hence, data from animal studies have provided the majority of information regarding cardiac LPL in diabetes." (PMID 34356640, 2021). "Although the majority of patients with diabetes and severe HTG have type 2 diabetes, severe HTG may occur in poorly controlled insulin deficient diabetes, where the combination of LPL deficiency and continued dietary fat intake are key factors." (PMID 33193106, 2020). "Lipoprotein lipase (LPL) is secreted by dysfunctional cardiomyocytes in diabetes." (PMID 32508749, 2020). "Hormone-sensitive lipase, which is activated in diabetes, lipoprotein lipase, which is often defective in diabetes, and the fatty acid transporter Cd36, which is involved in the FFA uptake, are regarded as main contributors of plasma levels of FFA and triglycerides." (PMID 30286142, 2018). "Are genetically determined differences in lipoprotein lipase (LPL)–mediated lipolysis and low-density lipoprotein cholesterol (LDL-C)–lowering pathways independently associated with risk of coronary disease and diabetes?" (PMID 30326043, 2018). "We also provide evidence consistent with the association with lower odds of diabetes being specific to the LPL pathway and not being a general association of lower triglyceride levels." (PMID 30326043, 2018). "Moreover, in obese subjects with type 2 diabetes mellitus, circulating AngII levels correlate with changes in body weight and tend to correlate negatively with change in LPL." (PMID 26447765, 2015). "However, decreased LPL activity and VLDL-R deficiency in diabetes cannot explain the increased fatty acid oxidation observed in these hearts, which is another characteristic feature of the diabetic state." (PMID 21773049, 2011). "Such a phenomenon could be potentially attributable to an array of physiological changes, including diminished postprandial triglyceride clearance, a reduction in lipoprotein lipase activity, an upsurge in ectopic fat deposition, as well as the higher rate of diabetes in the elderly." (PMID 38275402, 2024). "This article presents an overview of cardiac LPL, explains how the enzyme works, describes key molecules that regulate its activity and outlines how changes in LPL are brought about by physiological and pathological states such as fasting and diabetes, respectively." (PMID 34356640, 2021). "Patients with renal disease, whether associated with diabetes or not, have increased TG and remnant lipoprotein levels and decreased LPL and HL activity." (PMID 25120629, 2014). "For instance, metformin is used in diabetes treatment to activate AMP-activated protein kinase (AMPK), which boosts the expression and function of LPL in skeletal muscle, thus enhancing lipid metabolism." (PMID 40625358, 2025). "Using streptozotocin (STZ) to induce moderate diabetes in rats, we reported that like fasting, acute hypoinsulinemia stimulated AMPK phosphorylation, and resulted in an augmented coronary LPL activity." (PMID 39081272, 2024). "Mechanistically, a reduction in insulin after fasting or STZ-induced diabetes decreases glucose uptake in the heart resulting in activation of AMPK with stimulation of LPL translocation (see detailed review)." (PMID 39081272, 2024). "Accordingly, it was found that the content of LPL, a rate-limiting enzyme for the clearance of circulating TAG, was increased in rats’ models of acute and moderate diabetes." (PMID 37686357, 2023). "GCG, IRS1, VEGFA, STAT3, CCL2, CASP3, and APOE as diabetes mellitus-related proteins and SREBF1, LPL, PPARA, APOB, GPT, MAPK8, and FASN as NAFLD-specific proteins were identified as possible discriminating factors between the two studied diseases." (PMID 35154608, 2021).
diabetes (continued). "Maintaining a LPL- ANGPTL4 balance is essential, and considering LPL and ANGPTL4 as cardiac specific biomarkers would be advantageous in detecting the stage of diabetes and in treating cardiovascular complications accordingly." (PMID 34616362, 2021). "A study in diabetes showed a role of TLR4 in promotion of lipid metabolism and lipid accumulation through LPL expression and diabetes in cardiomyocytes of mice." (PMID 33395447, 2021). "Since lipoprotein lipase (LPL) is activated by insulin, triglycerides tend to accumulate when secretion of insulin deteriorates due to diabetes." (PMID 29089472, 2017). "Due to reductions in lipoprotein lipase activity, the TG levels readily increase and VLDL clearance decreases after eating in patients with diabetes, and the accumulation of VLDL increases." (PMID 24223651, 2013). "Other pre-diabetes and diabetes population studies also showed that the pancreatic β cell dysfunction can lead to elevation in HDL-C levels, and the mechanism may be associated with alteration in VLDL catabolism, decrease in apolipoprotein AI (ApoAI) levels and insufficient LPL functions." (PMID 22876749, 2012). "More recently, cardiac VLDL-R protein levels, as well as postheparin LPL activity, were found to decline significantly in STZ-induced diabetes." (PMID 21773049, 2011). "By contrast, patients with metabolic diseases, diabetes, and CVD have low circulating LPL levels." (PMID 40507147, 2025). "In the fibrate user group (n = 6), the LPL levels were significantly lower (43.4 vs. 62.5 ng/mL, p = 0.038), while the HOMA-IR values (2.3 vs. 1.4, p = 0.042), diabetes prevalence (33.3% vs. 4.8%, p = 0.018), and TG levels (178.5 vs. 105.0 mg/dL, p = 0.016) were significantly higher." (PMID 41156460, 2025). "Given the well-established molecular link between Sirt1 and PPARG signaling and the detrimental role played by PPARG in the context of MCM, we examined PPARG and PPARG-dependent genes LPL, PLIN, CD36, FAS and PPARA in cardiac specimens from diabetics and controls." (PMID 37957697, 2023). "• Glucose uptake and TCA cycle flux decreased, mitochondria was fewer in insulin-resistant offspring skeletal muscle of diabetes history. • O-GDM had decreased PPARGC1A in skeletal muscle. • Fatty acid flux into myotube and LPL expression were lower in offspring of T2DM parents." (PMID 37255932, 2023). "Even if tissue specificity can be resolved by using homogenates, the estimation of cardiac LPL from patients with diabetes would be inappropriate, as it would reflect total cardiac LPL and not the more pertinent functional pool at the coronary lumen." (PMID 34356640, 2021). "Regarding tissue-specific assessment, adipose tissue and skeletal muscle show low levels of LPL in homogenates following diabetes, with virtually no information available on the cardiac content of this enzyme." (PMID 34356640, 2021). "LPL mRNA levels in sc AT were lower in obese humans with diabetes compared to healthy individuals but not to obese patients without diabetes." (PMID 32321549, 2020). "Finally, the activities of the lipoprotein lipase (LPL) and lecithin cholesterol acyl transferase (LCAT) enzymes were also altered by diabetes and normalized by diosmin." (PMID 32977511, 2020). "Therefore, these four studies did not meet our screening criteria and were not directly related to diabetes and its related changes in LPL activity." (PMID 41373652, 2025). "Thus, agents that are capable of increasing cardiac LPL activity through the AMPK pathway may be useful for preventing NEFA uptake and lipotoxicity following diabetes." (PMID 39081272, 2024). "Lipoprotein lipase (LPL) is responsible for regulating FA delivery to the heart, and its function during diabetes has not been completely revealed." (PMID 39081272, 2024).
familial chylomicronemia syndrome (66 papers, 2008 to 2026). A rare autosomal recessive disease characterized by the buildup in the blood of fat particles called chylomicrons (chylomicronemia), severe hypertriglyceridemia, and the risk of recurrent and potentially fatal pancreatitis and other complications. "Biallelic rare pathogenic loss-of-function (LOF) variants in lipoprotein lipase (LPL) cause familial chylomicronemia syndrome (FCS)." (PMID 39858602, 2025). "Biallelic loss-of-function (LOF) variants in the LPL gene are the predominant cause of familial chylomicronemia syndrome (FCS) cases worldwide, accounting for ~80% of all cases." (PMID 39858602, 2025). "Familial chylomicronemia syndrome (FCS) is a rare autosomal recessive condition characterized by defective or absent LPL activity, most commonly caused by mutations in genes such as LPL, APOC2, APOA5, GPIHBP1, or LMF." (PMID 41393714, 2025). "LpL deficiency has been created in mice and reproduces many aspects of human familial chylomicronemia syndrome (FCS)." (PMID 39649171, 2024). "Mutations in the LPL gene can lead to type I hyperlipoproteinemia and LPL is also considered to be a key target for many lipid‐lowering agents." (PMID 38726415, 2024). "Mutations in LPL are involved in type I hyperlipoproteinemia and many disorders related to lipoprotein metabolism." (PMID 39050255, 2024). "Defects in LPL are a cause of familial chylomicronemia syndrome (or type I hyperlipoproteinemia) and of a form of deficiency characterized by hypertriacylglycerolemia." (PMID 38455763, 2024). "A recent review in 2024 reported that genetic studies have identified over 100 loss-of-function and functionally heterogeneous mutations in LPL associated with the development of LPL deficiency in individuals with Familial Chylomicronemia Syndrome." (PMID 39590382, 2024). "Common LPL gene mutations (Asp9Asn, Asn291Ser, Trp86Arg, Gly188Glu, Pro207Leu, Asp250Asn) associated with type I hyperlipoproteinemia have been detected in approximately 20% of patients with hypertriglyceridemia." (PMID 37510094, 2023). "Homozygous or compound heterozygous mutations in the LPL gene cause lipoprotein lipase deficiency (LPL deficiency or type I hyperlipoproteinemia, or familial chylomicronemia syndrome, OMIM 238600), a rare autosomal recessive disorder." (PMID 37510094, 2023). "The familial chylomicronemia syndrome (FCS) is an ultra rare disease caused by lipoprotein lipase (LPL) deficiency associated with potentially lethal acute pancreatitis risk." (PMID 37370069, 2023). "Inherited in an autosomal recessive manner, type I hyperlipoproteinemia is caused mainly by the loss-of-function mutation of the LPL gene." (PMID 35923617, 2022). "Compound homozygous or heterozygous mutations in the LPL gene cause Lipoprotein lipase deficiency (LPL deficiency or type I hyperlipoproteinemia) (OMIM, 238,600), a rare autosomal recessive condition." (PMID 35743896, 2022). "To date, more than 200 mutations in the LPL gene have been reported to result in type I hyperlipoproteinemia in the Human Gene Mutation Database (HGMD), while only a limited number of mutations have been evaluated for pathogenesis." (PMID 35923617, 2022). "We showed through bioinformatics analysis and in vitro experiments that these variants can affect the enzymatic activity, production, and/or secretion of LPL and cause type I hyperlipoproteinemia in both cases." (PMID 35923617, 2022). "In the present study, we systematically identified and characterized two novel compound heterozygous variants of the LPL gene in patients with type I hyperlipoproteinemia." (PMID 35923617, 2022). "Two novel compound heterozygous variants of LPL induced defects in the expression and function of LPL and caused type I hyperlipoproteinemia." (PMID 35923617, 2022).
familial chylomicronemia syndrome (continued). "It is estimated that approximately 20% of patients with hypertriglyceridemia carry only six common LPL gene mutations (Asp9Asn, Asn291Ser, Trp86Arg, Gly188Glu, Pro207Leu, Asp250Asn) associated with type I hyperlipoproteinemia." (PMID 35743896, 2022). "To conclude, we have described two novel compound heterozygous variants of LPL in patients with type I hyperlipoproteinemia, showing that all these variants are pathogenic by disrupting LPL mass and the enzymatic activity of LPL." (PMID 35923617, 2022). "The diagnosis of familial chylomicronemia syndrome is confirmed by genetic mutations of the lipoprotein lipase (LPL) and other genes functioning as cofactors for LPL." (PMID 34828789, 2021). "There are subjects with mutations in the gene encoding LPL or genes encoding proteins necessary for LPL function (familial chylomicronemia syndrome (FCS))." (PMID 35008488, 2021). "Severely compromised LPL activity causes familial chylomicronemia syndrome (FCS), which is associated with very high plasma triglyceride levels and increased risk of life-threatening pancreatitis." (PMID 31645434, 2020). "At the genetic level, severely elevated triglyceride levels resulting from familial chylomicronemia syndrome (FCS) are caused by homozygous or biallelic loss-of-function variants in LPL, APOC2, APOA5, LMF1, and GPIHBP1 genes." (PMID 32793115, 2020). "Deficiency in LPL activity in humans (type I hyperlipoproteinemia or familial chylomicronemia syndrome) is associated with massive chylomicronemia, low HDL-C levels, and recurrent attacks of pancreatitis when not controlled by a strict diet." (PMID 32849290, 2020). "Familial chylomicronemia syndrome (FCS) is caused by mutations in the lipoprotein lipase (LPL) and related molecules." (PMID 33246467, 2020). "ApoC2 functions as a cofactor for lipoprotein lipase (LPL) and its deficiency results in type I hyperlipoproteinemia." (PMID 31779116, 2019). "LPL, associated with TG, is a triglyceride hydrolase and a ligand factor for receptor-mediated lipoprotein uptake; mutations causing LPL deficiency have been implicated in type I hyperlipoproteinemia (NCBI: LPL, 2011)." (PMID 22994408, 2012). "Mutations of significant severity can cause LPL deficiency, potentially leading to Type I Hyperlipoproteinemia, whereas less critical mutations may be implicated in diverse abnormalities in lipoprotein metabolism." (PMID 40427755, 2025). "In addition to familial chylomicronemia syndrome, more than 200 mutations were reported in patients with LPL deficiency." (PMID 38455763, 2024). "LPL deficiency is one of the major causes of familial chylomicronemia syndrome." (PMID 37630727, 2023). "Severe mutations due to LPL deficiency cause type I hyperlipoproteinemia." (PMID 37697333, 2023). "Chylomicronemia syndrome (CS) may be due to very rare monogenic mutations in the genes encoding the LPL enzyme or its regulators leading to familial chylomicronemia syndrome (FCS) and with the phenotypical appearance of Fredrickson type 1 hyperlipoproteinemia." (PMID 35144640, 2022). "(B) Familial chylomicronemia syndrome (FCS) is a syndrome characterized by high levels of chylomicrons due to autosomal recessive mutation of the lipoprotein lipase (LPL) gene located on chromosome 8p21.3 or the Apolipoprotein C2 (APOC2) gene located on chromosome 19q13.32." (PMID 36012138, 2022). "Familial chylomicronemia syndrome (FCS) is a rare genetic disorder caused by LPL deficiency." (PMID 31645434, 2020). "Familial chylomicronemia syndrome (FCS), also known as type I hyperlipoproteinemia, is a rare autosomal recessive disease caused by loss-of-function mutations in the LPL gene or by mutations in genes encoding proteins or enzymes directly affecting LPL activity." (PMID 25889044, 2015). "The LPL deficiency often leads to in type I hyperlipoproteinemia." (PMID 24222897, 2013).